CD4 (CD4 molecule)
Diseases named in the same sentence as CD4 in open-access papers (continued):
Sharing a sentence is not in itself a finding about the gene and the disease.
Graves disease (35 papers, 2011 to 2025). Graves' disease is an autoimmune disorder that leads to overactivity of the thyroid gland (hyperthyroidism).It is caused by an abnormal immune system response that causes the thyroid gland to produce too much thyroid hormones. "Actually, the pathogenic factors in Graves' hyperthyroidism are the autoaggressive CD4+ cells which drive the maturation of the plasma cells and secretion of stimulatory autoantibody targeting thyrotrophin (TSH) receptor (i.e., TR-Ab)." (PMID 27721890, 2016). "In this study, we aimed to analyze differences in immune gene expression between a patient with TS, a healthy female, and a female patient with Graves’ disease using single-cell RNA sequencing (scRNA-seq) analysis of antigen-specific CD4(+) T cells." (PMID 39851522, 2025). "Graves’ disease, a female-predominant condition, exhibits adaptive immune response biased towards CD4(+) T cells." (PMID 39851522, 2025). "A shifted ratio of complex-to-oligomannose N-glycans was also found in Graves’ disease, where complex-type structures were partially replaced by oligomannose forms in CD4+CD25- in patients compared to healthy subjects." (PMID 41030447, 2025). "The absolute number of CD4/CD25/FOXP3 was lower in the Graves’ disease group than in Hashimoto’s thyroiditis group." (PMID 41307767, 2025). "Hypermethylation H3K4me3 along with methylation CpG sites in CD4+ and CD8+ was marked and their association with several T cell signaling genes also in Graves’ disease." (PMID 32899152, 2020). "In the case of Graves’ disease high acetylation of H3K27ac in CD4+ and CD8+ in PBMC was observed but low H4ac in PBMC." (PMID 32899152, 2020). "CXCR5+ CD4+ T cells were increased in the thyroid tissue of patients with Graves’ disease compared to control subjects." (PMID 31412566, 2019). "CD4(+) T cells gated single-cell RNA-sequencing was used to conduct a detailed comparison of gene expression patterns between a Turner syndrome patient, a healthy female, and a female with Graves’ disease." (PMID 39851522, 2025). "In this study, we used CD4(+) T cells gated single-cell RNA sequencing of peripheral blood mononuclear cell samples from a Turner syndrome patient, a healthy female, and a patient with Graves’ disease to identify differentially expressed genes." (PMID 39851522, 2025). "Most notably, Actinobacteria (p) presented protective effects on Hashimoto’s thyroiditis via CCR2 on myeloid Dendritic Cell (5.0%), and Bifidobacterium (g) showed facilitating effects on Graves’ disease through CD39+ CD4+ T cell %CD4+ T cell (5.0%) and CD14 on CD33+ HLA DR+ CD14dim (12.2%)." (PMID 39351300, 2024). "Aberrant CD4+ T cell function plays a critical role in the process of Graves’ disease (GD)." (PMID 29163513, 2017). "CD4+ T cells, CD8+ T cells, and macrophages are abnormally increased in patients with HT and Graves’ disease." (PMID 40364944, 2025). "Our study is aimed at detecting the expression of SLAM and SAP in patients with Graves' disease (GD) and analyzing the effect of SLAM/SAP on circulating blood CD4+CXCR5+Foxp3+ follicular regulatory T (Tfr) cells." (PMID 33987447, 2021). "Our finding of significantly decreased CD4/CD8 ratio is mismatched with in the HT group, and they also reported a significantly increased ratio in Graves’ disease, which is also contrary to our finding." (PMID 29706856, 2018). "A decrease in the CD4/CD8 ratio in hypothyroid Hashimoto's thyroiditis patients has long been observed, in contrast to the increase in the ratio in Graves' hyperthyroidism." (PMID 27721890, 2016). "Furthermore, CD4+ IL-21R+ T cells and CD19+ IL-21R+ B cells were also observed in Graves’ disease tissues." (PMID 31412566, 2019). "A study on patients with Graves’ disease found that their serum magnesium concentrations were lower than in normal individuals, and that the serum magnesium concentration was inversely related to the activation levels of CD3+, CD4+, CD8+T, and CD19+B cells." (PMID 29967483, 2018).
Graves disease (continued). "According to our results, the frequency of CD4/CD25/FOXP3, but not CD4+/CD25 + in Graves’ disease was lower than Hashimoto’s thyroiditis." (PMID 41307767, 2025).
renal carcinoma (35 papers, 2006 to 2025). A carcinoma arising from the epithelium of the renal parenchyma or the renal pelvis. "Meanwhile, we observed that CD127− CD8br AC and CD25 on CD39+ activated Tregs, and CD4 on TD CD4 in the T-cell maturation panel were correlated with an increased risk of renal carcinoma." (PMID 40958287, 2025). "Here, we report a novel founding that low ACO1 and IREB2 contents in renal cancer are linked to the decreased invasion of B cells, neutrophils, CD4+ T cells, dendritic cells, and CD8+ T cells, along with macrophages." (PMID 36059676, 2022). "Survival analysis showed that high overall TIICs proportion, the low proportion of resting mast cells and the high proportion of activated memory CD4 T cells were associated with poor prognosis of renal cancer patients." (PMID 34030645, 2021). "It was found that activated memory CD4 T cells and resting mast cells were significantly associated with the prognosis of renal cancer patients (HR = 9.4e + 05, p = 0.004 and HR = 3.7e – 03, p = 0.034, respectively)." (PMID 34030645, 2021). "The results showed that elevated proportion of activated memory CD4 T cells and decreased proportion of resting mast cells were associated with poor prognosis of renal cancer." (PMID 34030645, 2021). "In renal cancer, neutrophil infiltration is a high-risk indicator, while the large number of the emergence of CD4+ T-cells is a low-risk signature." (PMID 33204302, 2020). "In the TME of renal cancer, CD4 + T cells demonstrate significant heterogeneity across different aspects, reflecting the complexity of the TME." (PMID 41035074, 2025). "CD4+ T cell frequencies were increased in tumors of multiple independently derived renal cancer clones and were rescued upon Vhl addback." (PMID 38618956, 2024). "To verify these findings, we sorted CD4+CD25hi Tregs from human colorectal, gastric and renal cancer samples for the correlation analyses of mRNA expression." (PMID 39480507, 2024). "In renal cancer, high tumorous infiltration of CD4+ T cells indicated a poorer recurrence-free survival." (PMID 37215452, 2023). "The association of PTP4A3 expression with B cells, CD8+ T cells, CD4+T cells and neutrophil infiltration was confirmed in renal cancer using the GEPIA and TIMER databases." (PMID 34630392, 2021). "In the present study, a high proportion of activated memory CD4 T cells were related to poor prognosis of renal cancer patients." (PMID 34030645, 2021). "There was a negligible expression of CD177 on conventional CD4+ T cells (Tconv) in breast and renal cancers." (PMID 34599187, 2021). "The survival curves showed a low proportion of resting mast cells and a high proportion of activated memory CD4 T cells were related to poor prognosis of renal cancer patients (both p < 0.0001)." (PMID 34030645, 2021). "In summary, the analysis of 22 TIICs proportions in renal cancer samples showed elevated activated memory CD4 T cells proportion, and decreased resting mast cells proportion predicted poor prognosis in renal cancer." (PMID 34030645, 2021). "Tregs, identified as percentage of CD4+CD25hiFOXP3+ cells, were evaluated in 42 consecutive renal cancer patients." (PMID 29100374, 2017). "The role of Th2 cells is less clear but in patients with renal carcinoma and melanoma, circulating CD4+ cells display Th2-polarized (IL-5) responses to MAGE-6 epitopes in active disease and Th1-polarized (IFN-γ) responses in remission." (PMID 26075202, 2015). "Regarding the phenotypic aspects of cells, multi-regional genomic and single-cell transcriptomic sequencing in renal cancer has identified subsets of CD4 + T cells, such as CD4 + naive/central memory T cells and CD4 + Tregs, revealing their distinct tissue distribution." (PMID 41035074, 2025). "Elevated CD4+ activated memory T cells correlate with poorer renal cancer prognosis." (PMID 41584585, 2025).
renal carcinoma (continued). "In addition, CD4+ T cells promote renal cancer cell proliferation by regulating YBX1, and MDSCs accumulate in various tumors, promoting vascular survival and improving tumor immunity." (PMID 35571068, 2022). "Similarly, we found the expression of LILRB4 was higher on CD4+ T cells than on CD8+ T cells within tumor-infiltrating CD3+ T cells in the mouse renal carcinoma model RENCA." (PMID 33974041, 2021). "Report on lung cell carcinomas prove that COX-2 derived PGE2 plays a significant role in the transformation of regulatory T cells, and researchers have found that COX-2 derived PGE2 in renal cancer can transform CD4+FOXP3− T cells into CD4+CD25+FOXP3+ regulatory T cells to escape the immune system." (PMID 33767709, 2021). "A similar effect was found in CD4+ T cells restimulated and co-cultured with 786-O renal cancer cell line overexpressing PD-L1 on the cell surface, which strongly suggested the existence of universal mechanism of CD4+ T cell exhaustion induced by PD-L1-expressing cancers." (PMID 34439305, 2021). "However, some studies reported that increased CD4+T cell infiltration in renal cancer tissues was related to a worse prognosis." (PMID 32767974, 2020). "By the same token, IL-6 secreted by CD4+ T cells induces renal cancer cell EMT." (PMID 28846080, 2017). "Similarly, CD4+ cells from patients with stage I renal carcinoma showed predominantly Th1-polarized responses to EphA2, whereas CD4+ cells from later stages showed progressively more Th2-polarized responses." (PMID 26075202, 2015). "CD4 + T cells exhibit a spectrum of heterogeneity within the TME in various cancers, including renal cancer." (PMID 41035074, 2025). "We found that in renal cancer, the expression of PUSs significantly affects CD8 + and CD4 + T-cell infiltration." (PMID 39162904, 2024). "In the future work, the relationship between PTP4A3 expression and B cells and other T cells including CD4+ T cells, CD45RO+ memory T cells, regulatory T cell need to be explored in renal cancer." (PMID 34630392, 2021). "Hence, we speculated that the increased proportion of activated memory CD4 T cells contributed to inferior survival outcomes in renal cancer through enhanced secretion of IL-17, which might be one of the possible mechanisms and needed to be validated further in the future investigations." (PMID 34030645, 2021). "The level of CD4+ and CD8+ infiltration however, has been shown to be similar between subcutaneous and orthotopic colon or renal cancer models 49,50." (PMID 31754392, 2019). "Similarly to the effector T cell subsets, the frequencies of both CD4+CD25hiCD127lo and CD8+CD28-CD127loCD39hi Treg were significantly lower in the apparently unaffected renal tissue than in the autologous renal cancer tissue." (PMID 26824503, 2016). "Accordingly, the immunohistochemical staining with anti-CD3, CD4 and CD8 mAbs showed remarkable T cell infiltration in bladder and renal cancers as well as in the apparently free-of-tumor bladder tissue, while a rare T cell infiltrate was present in the apparently free-of-tumor kidney tissue." (PMID 26824503, 2016). "The frequencies of four effector T cell subsets, namely CD4+IFNγ+, CD8+IFNγ+, CD4+IL17+, CD8+IL17+ T lymphocytes, and two Treg subsets, CD4+CD25hiCD127lo and CD8+CD28-CD127loCD39hi Treg, were comparatively analyzed in the peripheral blood of bladder and renal cancer patients." (PMID 26824503, 2016).
schizophrenia (35 papers, 2007 to 2025). A major psychotic disorder characterized by abnormalities in the perception or expression of reality. "Among the studied immunophenotypes, only four showed significant relationships with the risk of schizophrenia: CD4+ T cells and T regulatory lymphocytes, HLA-DR on monocytes, and CD33dim HLA-DR+CD11b− (their increase reduced the risk of schizophrenia)." (PMID 39061465, 2024). "Epigenetically activated sites in T cells, especially cytokine-stimulated CD4+ T cells, were most consistently and significantly enriched for cis-diagnostic variants associated with either schizophrenia or MDD." (PMID 36243721, 2022). "We found significantly higher DRD3 gene expression in CD4+ T cells in schizophrenia; and higher DRD3 expression was associated with proportionally reduced counts of activated and memory Treg cells." (PMID 27244229, 2016). "Furthermore, our investigation revealed an association between the severity of schizophrenia symptoms and the T lymphocyte mitochondrial CD4+/CD8+ ratio." (PMID 38235140, 2023). "It regulates the survival and function of T cells by controlling cell death, thereby modulating the activity of Th1 and activated CD4+ T cells, indirectly participating in the occurrence and development of schizophrenia." (PMID 40242178, 2025). "Drug-naïve schizophrenia patients in acute-phase had higher levels of peripheral blood CD4+ T lymphocytes and B lymphocytes, higher PD-1 expression in B lymphocytes, and lower levels of CD8+ T lymphocytes." (PMID 38066312, 2023). "In summary, the relationship between the T lymphocyte mitochondrial CD4+/CD8+ ratio and the severity of schizophrenia symptoms, as well as its association with age, remains inconsistent and necessitates further research." (PMID 38235140, 2023). "The mitochondrial function of CD3+CD4+ lymphocytes in schizophrenia is significantly impaired, possibly due to persistent low-level inflammation." (PMID 38235140, 2023). "While some studies have reported an increase in the CD4+/CD8+ ratio in specific individuals with schizophrenia, there remains ongoing debate on this topic." (PMID 38235140, 2023). "We found that the difference in mitochondrial CD3+CD4+ counts between male overweight and normal weight schizophrenia patients was more pronounced compared to female patients." (PMID 38235140, 2023). "A 2013 meta-analysis describes an increase in the absolute level of CD3+ and CD4+ cells and an increase in the CD4/CD8 ratio in the blood of patients with schizophrenia relative to healthy donors." (PMID 35546942, 2022). "In the immune infiltration analysis, there was a significant difference in resting memory CD4 T cells between schizophrenia and healthy individuals." (PMID 35741729, 2022). "A meta-analysis of 16 studies of lymphocytes in schizophrenia vs. healthy controls showed a significant increase in the percentage of CD4 and CD56 (natural killer cells) in acutely ill patients." (PMID 30766494, 2018). "Clozapine has previously been shown to decrease production of IFN-γ and enhance IL-4 and IL-10 in poly (I:C)-stimulated PBMC cultures from schizophrenia patients, which suggests an effect on CD4+ T cell differentiation." (PMID 28356108, 2017). "The prior literature on other T cell subsets in schizophrenia includes repeated observations of an increased proportion of naïve T cells relative to CD45RA- CD4+ T-cells." (PMID 27244229, 2016). "Expression of the dopamine D3 (DRD3) receptor was significantly increased in clozapine-treated schizophrenia and covaried significantly with differentiated T cell classes in the CD4+ lineage." (PMID 27244229, 2016). "Furthermore, previous studies showed schizophrenia had disrupted lymphocyte subsets, and a meta-analysis demonstrated first-episode schizophrenia had elevated CD4/CD8 and significantly lower CD3%." (PMID 38233774, 2024).
schizophrenia (continued). "Additionally, overweight patients had significantly higher mitochondrial lymphocyte counts of CD3+ T and CD3+CD4+ T cells compared to schizophrenia patients with normal weight." (PMID 38235140, 2023). "In schizophrenia patients, the increase of CD4+ T cells was reported as well." (PMID 35844577, 2022). "However, according to other data, the level of T-helper cells, as well as the ratio of CD4 + / CD8 + in schizophrenia are reduced, and the patients have impairments of T-cell activation." (PMID 38601098, 2021). "Furthermore, the ratio of IL-17 and IL-10 expression in NK cells and CD4+ T cells was significantly increased in patients with stable schizophrenia." (PMID 33182582, 2020). "It is appealing that another group of significant pathways including the Fc-epsilon receptor I signaling in mast cells, the TCR signaling in CD4+ T cells and IL2-mediated signaling events highlight the importance of immune system mediated pathways in the key role of schizophrenia susceptibility." (PMID 24564241, 2013). "Also, patients with schizophrenia had significantly higher CD4+/CD8+ ratio (P < 0.01)." (PMID 38066312, 2023). "It has been suggested that CD4/CD8 ratio may be a state marker of acute exacerbation of schizophrenia, because the results of a meta-analysis showed that CD4/CD8 ratio was significantly increased in first-episode schizophrenia patients, while it was significantly decreased after drug treatment." (PMID 38066312, 2023). "A meta-analysis indicates that individuals diagnosed with schizophrenia exhibit elevated levels of CD3 + and CD4 + cells, together with an augmented CD4/CD8 ratio." (PMID 40535971, 2025). "Compared to the control group, schizophrenia patients had a higher level of mitochondrial lymphocyte count in CD3+ T, CD3+CD4+ T, and CD3+CD8+ T lymphocytes." (PMID 38235140, 2023). "The mitochondrial lymphocyte count indices of CD3+ (t = 3.535, p = 0.001), CD3+CD4+ (t = 2.953, p = 0.004), and CD3+CD8+ (t = 3.498, p = 0.001) T lymphocytes in the schizophrenia group were lower compared to the control group." (PMID 38235140, 2023). "The results showed that mitochondrial lymphocyte counts of CD3+ T, CD3+CD4+ T, and CD3+CD8+ T cells in schizophrenia patients were higher than in the control group (p < 0.05)." (PMID 38235140, 2023). "Mutant Disc1-L100P mice, a genetic model of schizophrenia, displayed an increase in CD3+CD4+ Th cells and a decrease in CD3+CD4+CD25+ Treg cells." (PMID 35844577, 2022). "According to a meta-analysis of 16 works, the level of CD4 + T-helper cells, CD16 + CD56 + NK cells, naive B-cells and CXCR5 + memory T-cells, was increased among those with schizophrenia." (PMID 38601098, 2021). "A study of 18 patients with schizophrenia (17 treated with clozapine) vs. 18 healthy persons found elevated monocytes, NK cells, naïve B cells and CXCR5+ memory CD4 cells in the schizophrenia group, and decreased number of DC and several T cells populations." (PMID 30766494, 2018). "In conclusion, our study confirmed that there are certain characteristic changes in immune cells in patients with acute schizophrenia, such as an increase in CD4/CD8 ratio, which can provide some support for the immune hypothesis of schizophrenia." (PMID 38066312, 2023). "Moreover, according to the results of a meta-analysis focused on schizophrenia, absolute blood counts revealed a significant increase in total lymphocytes, CD3, and CD4, as well as in the CD4/CD8 ratio." (PMID 35269952, 2022). "Schizophrenia cases had increased relative numbers of NK cells, naïve B cells, CXCR5+ memory T cells and classical monocytes; and decreased numbers of dendritic cells (DC), HLA-DR+ regulatory T-cells (Tregs), and CD4+ memory T cells." (PMID 27244229, 2016).